PROM2 (prominin 2)
Diseases named in the same sentence as PROM2 in open-access papers (continued):
Sharing a sentence is not in itself a finding about the gene and the disease.
tumor (12 papers, 2020 to 2025). "PTPN22 has the most significant multitarget intervention potential, while FAM175B and PROM2 are linked to tumor and inflammation pathways, and the specific interactions of LRRTM4 may guide precision treatment strategies." (PMID 40869128, 2025). "CDH1 expression was significantly lower in PROM2+ than in PROM2‐ tumours (p = .002) whereas other markers including VIM had an increased expression (p = .002)." (PMID 38515278, 2024). "The data indicated that cisplatin treatment reduced the volume and weight of tumors, while knockdown of PROM2 further inhibited the tumor growth." (PMID 37665741, 2023). "All these results suggested that PROM2 knockdown suppressed tumor growth through enhancing the cisplatin sensitivity." (PMID 37665741, 2023). "PROM2 promoted ferroptosis resistance in tumor cells through stimulating the production of ferritin‐containing exosomes and multivesicular bodies and increasing ferritin export." (PMID 35373463, 2022). "In conclusion, it is our novel discovery that RP11-89 induces tumor cell proliferation and migration, promotes tumorigenesis and inhibits cell cycle arrest via the miR-129-5p/PROM2 axis in BLCA." (PMID 34728613, 2021). "It demonstrated that the expression of G6PD, EGFR, CHMP6 and PROM2 were elevated in the tumor tissues." (PMID 34885178, 2021). "The expression level of PROM2 was elevated in BLCA tissues compared with non-tumor tissues and negatively correlated with the relative expression of miR-129-5p via analysis of the starBase database using TCGA cohort as reference." (PMID 34728613, 2021). "Upregulation of PROM2 increased (while downregulation of PROM2 decreased) both the tumor volume and weight in vivo with gemcitabine treatment." (PMID 32123287, 2020). "Weekly measurements of the luminescence signal showed that overexpression of PROM2 accelerated the growth rate of the tumor compared with vector control cells, while silencing of PROM2 inhibited tumor growth." (PMID 32123287, 2020). "Using immunostaining, we also found a significantly larger number of cells expressing the EMT markers ZEB1 and SNAIL/SLUG in PROM2+ tumours (respectively 68 ± 5 and 82 ± 6%) compared with PROM2‐ tumours (respectively 7 ± 6 and 11 ± 4%, p < .01 for the two markers)." (PMID 38515278, 2024). "Moreover, the miR-129-5p/PROM2 axis is utilised by RP11-89 to promote tumour cell proliferation and migration, boost tumorigenesis and hinder cell cycle arrest." (PMID 39267831, 2024). "In vivo experiments confirmed that PROM2 knockdown could inhibit tumor growth and increase the sensitivity of tumor cells to cisplatin." (PMID 37665741, 2023). "In addition, several studies have shown that PROM1 and PROM2-targeted therapies are promising for the prevention of tumor development." (PMID 31164716, 2020). "Finally, as we compared the genes that correlated with PROM1 or PROM2 in each individual tumor type, we observed a substantial number of commonly correlated genes with the same correlation direction and we observed no commonly correlated genes with the reverse correlation direction." (PMID 31164716, 2020). "PROM2 up-regulation in NSCLC can attenuate the sensitivity of NSCLC cells to cisplatin and promote the proliferation, migration and invasion of tumor cells." (PMID 37665741, 2023). "In this study, we screened 19 genes associated with ferroptosis, of which 10 FerDEGs such as TLR4, KRAS and HSF1 were highly expressed and 9 FerDEGs such as MUC1, PROM2 and MT1G were lowly expressed in tumour tissue." (PMID 36936437, 2023). "In that study, HOXC11 overexpression rescued ART-induced effects on proliferation, migration, apoptosis, and ferroptosis by activating PROM2/PI3K/AKT signaling, whereas PROM2 silencing restored sensitivity to ART and tumor suppression both in vitro and in vivo." (PMID 40826138, 2025).
tumor (continued). "The strong positive correlation of SNRPA1, TMED10, and PROM2 with suppressive immune regulators like IDO1 and VTCN1, and negative correlation with Th1 and MAIT cell infiltration, suggest that these genes may contribute to an immune-evasive tumor microenvironment." (PMID 40826138, 2025).
adenocarcinoma (1 paper, 2023). A common cancer characterized by the presence of malignant glandular cells. "Moreover, univariate overall survival analysis of these individual 10 genes overexpressed in adenocarcinoma revealed a dramatic prognosis, the worst being C1QTNF6 and PROM2 overexpression." (PMID 38132167, 2023).
cardiac disease (1 paper, 2024). "For instance, thanks to the analysis of atrial samples from patients, we reported that Prom2 increased in aged human samples with HFpEF, suggesting a causative link between Prom2 expression and senescence‐associated cardiac disease." (PMID 38757782, 2024).
retinopathy (1 paper, 2017). "Two of these were coding indel variants in the following genes: FOXI3 (chr17:38,032,793) and PROM2 (chr17:34,827,666), but neither are plausible candidates for retinopathy." (PMID 28813472, 2017).
PROM2 also shares sentences with these, for which no sentence is quoted: blood cancers (1 paper); cardiomyopathy (1); cervical cancer (1); esophageal cancer (1); lymph node metastases (1); lymphoma (1); myeloma (1); renal cell carcinoma (1); renal chromophobe cell carcinoma (1); sarcoma (1); virus infection (1).